SIK2 (salt inducible kinase 2)
Diseases named in the same sentence as SIK2 in open-access papers (continued):
Sharing a sentence is not in itself a finding about the gene and the disease.
melanoma (2 papers, 2011 to 2023). A malignant, usually aggressive tumor composed of atypical, neoplastic melanocytes. "Here we report that flavonoids with an O-methyl group at their 4′ position efficiently inhibit SIK2 action in cultured melanoma cells and promote the melanogenic program in a TORC1-dependent manner." (PMID 22022544, 2011). "GSK-3 beta is capable of phosphorylating (activating) sites in the activation loop of SIK1/2, and the activated SIK1/2 proteins are stable, suggesting that B16F10 melanoma cells that have been treated with GSK-3 beta inhibitors have low levels of SIK2, which would promote melanogenesis." (PMID 22022544, 2011). "However, in HEK293 cells and B16F10 melanoma cells, 4′-O-methylflavone inhibited SIK2 more efficiently, suggesting several mechanisms exist by which flavones can inhibit SIK2 in cultured cells." (PMID 22022544, 2011). "When 4′-O-methylfisetin was added into the culture medium of B16F10 melanoma cells, the SIK2-mediated suppression of CREB activity was weakened and melanogenesis was strongly promoted, suggesting that eumelanogenesis in fisetin-treated mice might be induced by 4′-O-methylfisetin." (PMID 22022544, 2011). "Because one of the representative phenomena of SIK2 inhibition is the promotion of melanogenesis, we employed a melanogenesis assay using B16F10 melanoma cells to evaluate SIK2-inhibitory flavonoids." (PMID 22022544, 2011). "We have shown that 4′-O-methyl flavones can inhibit SIK2 activity and promote melanogenesis via the activation of TORC1 in B16F10 melanoma cells." (PMID 22022544, 2011). "Exposure of B16F10 melanoma cells to UV light results in the immediate nuclear translocation of TORC1, which is inhibited by SIK2." (PMID 22022544, 2011). "However, fisetin neither inhibited the CREB-inhibitory activity of SIK2 nor promoted melanogenesis in B16F10 melanoma cells." (PMID 22022544, 2011). "This hypothesis is also supported by the observation that 3′-O-methylflavones, such as isorhamnetin and geraldol, do not inhibit SIK2 in vitro, while they weakly induce melanogenesis in B16F10 melanoma cells." (PMID 22022544, 2011). "Because 4′-O-methylfisetin did not activate ERK in B16F10 melanoma cells, the upregulation of TORC activity by SIK2 inhibition has been suggested be a beneficial strategy for the treatment of neuronal diseases, and fisetin or 4′-O-methylfisetin may be helpful to perform this strategy." (PMID 22022544, 2011).
osteosarcoma (2 papers, 2018 to 2025). A usually aggressive malignant bone-forming mesenchymal neoplasm, predominantly affecting adolescents and young adults. "This suggests that inhibiting the expression of SIK2 can effectively inhibit the migration and invasion of human osteosarcoma cells." (PMID 39634133, 2025). "The mechanism by which SIK2 inhibits the proliferation, migration, and invasion of osteosarcoma was also explored for the first time." (PMID 39634133, 2025). "Silencing of USP1 was shown to target SIK2 to inhibit colony formation capacity and invasiveness of osteosarcoma cells by stimulating apoptosis." (PMID 29774109, 2018). "In this study, lentivirus-mediated RNA interference specifically inhibited the expression of SIK2 and significantly inhibited the proliferation and invasion of osteosarcoma cells, suggesting that SIK2 plays an important role in the occurrence, development, invasion, and metastasis of osteosarcoma." (PMID 39634133, 2025). "Together, the results show that RNA interference can significantly inhibit the proliferation and invasion of U2OS cells, and SIK2 may thus play an important role in the occurrence and development of osteosarcoma." (PMID 39634133, 2025). "However, irrespective of this dichotomy, the function and mechanism of SIK2 in osteosarcoma tumorigenesis and progression have yet to be elucidated." (PMID 39634133, 2025). "SIK2 may be a potential molecular target for osteosarcoma therapy, and the present findings provide new information about the development and progression of osteosarcoma." (PMID 39634133, 2025).
ovarian tumor (2 papers, 2021 to 2022). "Herein, we intended to develop a “smart” kinase‐triggered gel‐to‐solution transition strategy for local delivery and controlled release of SIK2 inhibitors at ovarian tumor sites to efficiently inhibit proliferation and metastasis of the tumor." (PMID 35618488, 2022). "In summary, to improve the inhibitory efficacy of a SIK2 inhibitor HG on ovarian tumor growth and metastasis, we rationally designed a hydrogelator Nap‐S and coassembled HG with the hydrogelator to form a hydrogel Gel Nap‐S+HG." (PMID 35618488, 2022). "In the cholesterol synthesis pathway, SREBP2 is upregulated by salt-inducible kinase 2 (SIK2), an AMPK-related kinase, and mitochondrial elongation factor 2 (MIEF2)-activated PI3K/AKT or ROS/AKT/mTOR signaling, thus, leading to the promotion of ovarian tumor growth." (PMID 34820325, 2021).
adenovirus infection (1 paper, 2014). "To test these hypotheses we performed short hairpin RNA interference -mediated knockdown of the SIK isoforms (singly and in combination) using adenovirus infection of SIK2-null mouse primary hepatocytes." (PMID 25088745, 2014).
allergic disease (1 paper, 2022). An immune response that occurs following re-exposure to an innocuous antigen, and that requires the presence of existing antibodies against that antigen. "The SIK2 locus, located downstream of POU2AF1, was previously reported to associate with allergic diseases." (PMID 35753705, 2022).
B-cell lymphoma (1 paper, 2022). "Notably, several studies suggest SIK2 (and other Salt-inducible kinases) playing a role in the metabolism of B-cell lymphoma and AML." (PMID 35994503, 2022).
brain tumor (1 paper, 2015). "Our next project will focus on how B55gamma regulates SIK2 through the association and how to target B55gamma-SIK2-S6K pathway to develop therapeutic strategies for the treatment of human brain tumor patients." (PMID 25792973, 2015).
breast tumors (1 paper, 2018). "Analysis of patient specimen and clinical data showed that SIK2 expression is downregulated in breast tumors and associated with patients’ survival, especially for basal subtype, suggesting its prognostic potential." (PMID 29774109, 2018). "E-TABM RNA sequencing dataset showed a statistically significant reduction of SIK2 expression in advanced stage of breast tumors (n=19, stage 3-4) as compared to early tumor stages (n=26; stage 1)." (PMID 29774109, 2018). "Therefore, in breast tumors, we suggest that SIK2 may function as a metastasis inhibitor via simultaneous blockage of Ras/ERK and PI3K/Akt pathways." (PMID 29774109, 2018). "Therefore, we conclude that SIK2 suppresses tumor progression, at least in part, through the inhibition of proliferation as well as survival capacities of the breast tumor cells, which can conceivably be mediated via simultaneous inhibition of Ras/ERK and PI3K/Akt signaling pathways." (PMID 29774109, 2018).
cardiac ischemia (1 paper, 2024). "Sik2 deletion suppresses hypertrophic response and reduces infarct area and cardiac fibrosis in MI induced by coronary artery ligation, suggesting that SIK2 deficiency protects against cardiac ischemia." (PMID 39081779, 2024).
colon cancer (1 paper, 2020). "FuSiOn identified ten kinases (BMP2K, DCLK3, LIMK2, MAP2K5/MEK5, MAP3K3/MEKK3, ROS1, SIK2, TAOK2, ULK1, and ULK2) whose depletion mimicked the phenotypic effect of p62 depletion in HCT116 colon cancer cells." (PMID 33101709, 2020).
gastric tumours (1 paper, 2020). "Thus, our results showed a statistically significant increase of SIK2 mRNA and protein expression in advanced stages of gastric tumours compared to lower grade tumors." (PMID 32082487, 2020).
Hypercalcemia (1 paper, 2023). An abnormally increased calcium concentration in the blood. "Ubiquitous/inducible SIK1/SIK2/SIK3 deletion caused modest increases in trabecular bone mass, with dramatic 1,25-vitamin D–mediated hypercalcemia." (PMID 36862513, 2023). "Global- and kidney-specific Sik2/Sik3 mutant mice showed Cyp27b1 upregulation, elevated serum 1,25-vitamin D, and PTH-independent hypercalcemia." (PMID 36862513, 2023).
intracerebral hemorrhage (1 paper, 2025). A cerebrovascular disorder characterized by bleeding into one or both cerebral hemispheres including the basal ganglia and the cerebral cortex. "Additionally, in microglia of mice with intracerebral hemorrhage, SIK2 inhibition reduced inflammation and ameliorated neurological dysfunction." (PMID 40135564, 2025).
ischemia (1 paper, 2022). A hypoperfusion of the BLOOD through an organ or tissue caused by a PATHOLOGIC CONSTRICTION or obstruction of its BLOOD VESSELS, or an absence of BLOOD CIRCULATION. "Compared with the sham group, the level of SIK2 decreased in the ischemia group and the reperfusion group, and the reperfusion group decreased more significantly than the ischemic group." (PMID 35586047, 2022).
lymph node metastasis (1 paper, 2021). "Given that SIK2 was downregulated in GC and its downregulation was correlated with lymph node metastasis and shorter survival, it is reasonable to postulate that loss of SIK2 augments GC cell aggressive behavior." (PMID 33128264, 2021). "Notably, the low expression level of SIK2 was positively correlated with lymph node metastasis (P < 0.0001), clinical stage (P = 0.0025), lymphatic invasion (P = 0.0055) and nerve/venous invasion (P = 0.0291)." (PMID 33128264, 2021).
primary sclerosing cholangitis (1 paper, 2018). "Additional common variant SNPs in kinases known to export Class IIA HDACs via phosphorylation, including SIK2 and PRKD2, are also associated with primary sclerosing cholangitis, suggesting aberrant regulation of HDAC7 nuclear export as a causative mechanism." (PMID 29664401, 2018).
Salmonella Infections (1 paper, 2023). Infections with bacteria of the genus SALMONELLA. "Indeed, SIK2 has recently been found to limit Salmonella infection; SIK2 KD in epithelial cells causes host cytoskeletal dysfunction, compromising Salmonella-containing vacuole integrity and resulting in cytosolic escape and bacterial hyperproliferation." (PMID 36731029, 2023).
sarcoma (1 paper, 2022). A usually aggressive malignant neoplasm of the soft tissue or bone. "Expression of SIK1 was the highest in DSRCT compared to other sarcomas, while expression levels of SIK2, SIK3 and LKB1 in DSRCT were similar to other sarcomas." (PMID 35443736, 2022).
steatosis (1 paper, 2022). Increased lipid within the cytoplasm of cells. "SIK2 has been shown to play an important role in various biological processes, including gluconeogenesis, neuronal survival, melanogenesis, hepatic steatosis, centrosome splitting, reprogramming of glucose metabolism, as well as fatty acid, cholesterol syntheses and paclitaxel chemosensitivity." (PMID 35278271, 2022).
uveal melanoma (1 paper, 2023). A melanoma derived from melanocytes of the uveal tract. "Indeed, our data also show that LKB1‐ or SIK2‐deficient uveal melanoma cells are more sensitive and vulnerable to disruption of Ca2+ homeostasis and oxidative stress." (PMID 37966164, 2023). "Enhanced mtROS level was detected in LKB1‐KO and SIK2‐KO uveal melanoma cells compared to the control cells." (PMID 37966164, 2023). "A genetic screen was launched to identify actionable vulnerabilities and uncovered the critical role of the kinases LKB1 and SIK2 in constraining metastatic uveal melanoma cell growth." (PMID 37966164, 2023). "Therefore, our data show that SIK2 is critically required downstream LKB1 to constrain uveal melanoma cell proliferation." (PMID 37966164, 2023). "We further demonstrate that combination of an SLC8A1 inhibitor and a mitochondria‐targeted antioxidant promotes enhanced cell death efficacy in LKB1‐ and SIK2‐negative uveal melanoma cells compared to control cells." (PMID 37966164, 2023). "Interestingly, while sgRNAs targeting SIK2 were enriched in our CRISPR/Cas9 kinome screen, sgRNAs for other LKB1 downstream targets were not (Dataset EV1), thereby suggesting that in uveal melanoma, LKB1 operates through SIK2 regulation." (PMID 37966164, 2023).
tumor (41 papers, 2015 to 2025). "According to most reported research, SIK1 is considered a tumor suppressor, while SIK2 and SIK3 are often associated with tumor promotion." (PMID 39063214, 2024). "Given the context-dependent tumor-promoting and -suppressing roles of SIK2, administration of SIK2 inhibitors in GPCR-mutated or other overactive cAMP-PKA cancer types should be attempted with extremely caution to avoid potential pro-tumor effects." (PMID 30723708, 2019). "Our data showed B55gamma associates with and stabilizes SIK2 which was indispensably participated in the inhibition of S6K-dependent growth regulation to keep tumor cell survival under glucose depletion." (PMID 25792973, 2015). "Where all genes, except for MAOA,CLU, and SIK2, were associated with poor tumour prognosis." (PMID 40028162, 2025). "SIK2 is involved in regulating lipid metabolism and synthesis and is associated with cell survival and cell cycle regulation which is also enriched in high Gleason tumours." (PMID 39578642, 2025). "Thus, research into the mechanism of SIK2 loss will help future scholars better understand tumor transformation in breast tissue and design new treatment strategies." (PMID 30723708, 2019). "Thus, each of these individual targets could serve as diagnostic marker of metastasis, with SIK2 being a novel marker for tumor development." (PMID 32082487, 2020). "Collectively, these insights confirm SIK2 as a central regulator of lipid biosynthesis in ovarian cancer, further validating the PI3K/AKT axis as a pivotal node in tumor‐associated metabolic reprogramming." (PMID 40740483, 2025). "SIK2 has been shown to act as a potential tumor promoter in ovarian, prostate, and colorectal cancers." (PMID 39634133, 2025). "Elevated SIK2 levels were found to be correlated with reduced tumor regression and poorer prognosis in LARC patients undergoing nCRT." (PMID 39877288, 2025). "Critically, among LARC patients who received nCRT, the proportion of patients with high SIK2 expression in pre‐treatment biopsies in the incomplete tumor regression group was significantly higher than that in the complete tumor regression group (GSE133057)." (PMID 39877288, 2025). "Increased SIK2 expression correlated with reduced tumor regression and poorer outcomes in LARC patients undergoing neoadjuvant chemoradiotherapy." (PMID 39877288, 2025). "Noticeably, SIK2 overexpression group mice had smaller tumor volume and tumor weight with decreased Ki67 staining compared with control mice." (PMID 36263177, 2022). "SIK2 inhibitors enhance olaparib sensitivity and inhibit tumor cell growth in both BRCA1/2 mutant and wild-type cancer cells." (PMID 35642638, 2022). "Salt inducible kinase 2 (SIK2) has been validated to exert tumor-promoting functions in a variety of cancers, including TNBC." (PMID 34353336, 2021). "Similar to AMPK, SIK2 has a dual role functioning as oncogenic driver or tumor suppressor in different cancer cell types." (PMID 33128264, 2021). "Together, the results of the cell line-based and the patient tumor-derived 3D-spheroid assays support the clinical significance of the combination SIK2 inhibition with paclitaxel." (PMID 34359562, 2021). "SIK2 has been shown to act as a potential tumor promoter in ovarian, prostate, osteosarcoma and colorectal cancers." (PMID 33128264, 2021). "Although SIK2 presents as a oncogenic marker on most occasions, a few studies have also revealed it to be a tumor suppressor." (PMID 33128264, 2021). "SIK2 is a member of the adenosine 5′-monophosphate-activated protein kinase (AMPK) subfamily that positively regulates tumor growth and metastasis." (PMID 32854207, 2020). "In this study, we focused on fly homologs of Sik2 and Sik3, their importance for development of the retina, and their involvement in tumor progression." (PMID 32542037, 2020).
tumor (continued). "The SIK2 overexpression group exhibited a much faster tumor growth than the control group, whereas the tumor growth-promoting effect of SIK2 was attenuated by knockdown of SREBP1c or SREBP2." (PMID 31932581, 2020). "Taken together, this study shows that fly Sik2 and Sik3 can promote tumor formation, that proper regulation of Sik2 and Sik3 is required for normal eye development, and that Siks functionally interact with the Notch pathway." (PMID 32542037, 2020). "While the contribution of Siks was less obvious in the stronger “eyeful” background, in the “sensitized” background changes in Sik2 levels clearly induce tumor-like structures." (PMID 32542037, 2020). "The expression level of SIK2 in cancers is significantly higher than that in adjacent and surrounding normal tissues, which suggests that SIK2 is critical in tumorigenesis and tumor development." (PMID 30723708, 2019). "Then it will promote lipids absorption and synthesis, and the abundant lipids in tumor cells provide substrates for structural, signaling, and metabolic purposes, which explains why SIK2 act as a tumor suppressor in PDA." (PMID 30723708, 2019). "While SIK2 is deemed to be a tumor promoter in most cases, in the context of GNAS mutated PDA, it is supposed to be a tumor suppressor, mainly because SIK2 plays different roles in different tissue and cells, similar to cAMP/PKA signaling." (PMID 30723708, 2019). "More investigations are necessary to clarify these issues and promote the use of SIK2 inhibitors in tumor therapy." (PMID 30723708, 2019). "While most studies reveal SIK2 to be a tumor promoter, some claims indicate that SIK2 provides protection from cancer." (PMID 30723708, 2019). "Recent reports demonstrated the link between FA oxidation and cancer cell proliferation and survival through activation of salt-inducible kinase-2 (SIK2) in tumour cells co-cultured with omental adipocytes." (PMID 30765860, 2019). "Further evaluation of these small molecules is necessary to achieve potent SIK2 inhibition in the uncontrolled signaling pathways of tumor cells while preserving the homeostatic and tumor-protective functions of SIK2 in other cell types." (PMID 30723708, 2019). "Salt Inducible Kinase2 (SIK2) has been shown to contribute to tumorigenesis in multiple tumor types in a dichotomous manner." (PMID 29774109, 2018). "Next, we investigated SIK2 protein expression in normal mammary gland and primary tumor samples collected from patients." (PMID 29774109, 2018). "A further study identified salt-inducible kinase 2 (SIK2) as a mediator between tumor cells and adipocytes." (PMID 30013512, 2018). "For example, the Cagan lab showed that members of the conserved AMP activated kinase family, Drosophila Salt Inducible Kinases 2 and 3 (SIK2 and 3), were required for tumor growth specifically on a high sugar diet." (PMID 30567377, 2018). "Mature adipocytes enhanced intracellular calcium ions in tumor cells and induced the auto phosphorylation of SIK2, which then inhibited ACC and activated phosphoinositol 3 kinase–protein kinase B (PI3K/AKT) signaling." (PMID 30013512, 2018). "We then analyzed SIK2 transcript levels directly by q-RTPCR using a cDNA array which included 23 tumor samples ranging from stage I to IIIC and 2 normal breast samples for the comparison." (PMID 29774109, 2018). "Reducing SIK2/3 in ras1G12V;csk−/− animals (sik2RNAi,ras1G12V;csk−/−) suppressed diet-enhanced Ras/Src-tumor growth." (PMID 26573956, 2015). "Conversely, expression of a constitutive active isoform of SIK2 (sik2CA) in Ras/Src-activated cells (ras1G12V;csk−/−,sik2CA) was sufficient to promote Ras/Src-dependent tumor overgrowth even in a control diet." (PMID 26573956, 2015). "SIK2 expression was significantly higher in tumor cells and tissues than in normal counterparts." (PMID 39877288, 2025). "In contrast, SIK2 may serve as a tumor suppressor in gastric cancer and pancreatic ductal adenocarcinoma." (PMID 39634133, 2025).